IGFBP4 (insulin like growth factor binding protein 4)
Diseases named in the same sentence as IGFBP4 in open-access papers (continued):
Sharing a sentence is not in itself a finding about the gene and the disease.
atherosclerosis (11 papers, 2012 to 2025). A disease characterized by the build-up of fatty material and calcium deposition in the arterial wall resulting in partial or complete occlusion of the arterial lumen. "In a study of patients with T2D and healthy controls, IGFBP-4 fragment levels were associated with the normalized wall-index, which is a measure of carotid artery remodeling and accelerated atherosclerosis." (PMID 30061864, 2018). "Our findings support the hypothesis that the Stanniocalcin-2/PAPP-A/IGFBP-4 axis is of remarkable importance in the vascular response to injury and in atherosclerosis and plays an important role in the risk stratification of STEMI patients." (PMID 29712555, 2018). "Although studies focusing on IGFBP4 in the field of atherosclerosis research have been relatively scarce, there have been reports of IGFBP4 levels affecting various biological behaviors, particularly in cancer-related diseases." (PMID 38760675, 2024). "For example, when PAPPA, the protease of IGFBP4, was genetically overexpressed in atherosclerosis models (APOE-KO), IGF bioavailability was enhanced due to reduced IGFBP4, resulting in a more severe atherosclerotic plaque formation." (PMID 36351970, 2022). "When the PAPP-A protease that cleaves IGFBP-4 was knocked down in a mouse model of atherosclerosis (ApoE KO), there was decreased formation of atherosclerotic lesions." (PMID 29686648, 2018). "Studies suggest that intact IGFBP-4 modulates cardiac development and cardiomyocyte differentiation and is actively involved in the development of atherosclerosis, with high expression levels in aorta lesional areas." (PMID 30061864, 2018). "Additionally, elevated expression level of IGFBP4 was detected in the atherosclerotic plaque and blood samples from people with atherosclerosis, suggesting a unique regulatory role for IGFBP4 in the plaque dynamics through KLF15/IGFBP4 axis." (PMID 40806552, 2025). "It implies that IGFBP4 could not only protect blood vessels from atherosclerosis but also potentially promote plaque stability, especially in the advanced stages of atherosclerosis." (PMID 38760675, 2024). "Further studies will, however, be required to assess the effects of elevated PAPP-A concentrations on autocrine and paracrine mechanisms for the exacerbation of atherosclerosis procession and plaque rupture through IGFBP-4 cleavage and enhanced local IGF-I bioavailability." (PMID 22997483, 2012). "Rare cells expressing FB-like (I-cluster 12, Pi16+, Igfbp4+, and Dpep1+) or MΦ-like genes (I-cluster 14, Lgals3+, Cd68+, and Ptprc+) had low expression of the eYFP lineage label, suggesting that these cells were not derived from VSMCs, similar to what has been proposed in atherosclerosis." (PMID 40577585, 2025). "Studies suggest that IGFBP-4 may be involved in inhibiting atherosclerosis." (PMID 29686648, 2018). "IGFBP-4, also an abundant IGFBP, has been suggested in numerous studies to be directly involved in the inhibition of atherosclerosis." (PMID 30061864, 2018). "PAPP-A may promote the development of atherosclerosis, plaque instability, and plaque rupture mainly through PAPP-A, IGFBP-4, and IGF-I/IGF-IR signal transduction systems, as well as interaction with other inflammatory cells and inflammatory factors." (PMID 38073653, 2023). "Consequently, different assays that measure IGFBP-4 as the cleaved substrate of active PAPP-A have been developed, on the basis that it may be reflective of PAPP-A enzymatic activity and may reflect plaque burden serving as marker of atherosclerosis." (PMID 29712555, 2018).
diabetes (9 papers, 2002 to 2024). "The association between glycosylated hemoglobin (HbA1c) and insulin-like growth factor-binding protein 4 with an increased risk of osteoarthritis validates the link between diabetes and osteoarthritis risk." (PMID 39172202, 2024). "Of the top 20 beta cell disallowed genes, IGF1 showed the strongest association with diabetes status (p = 0.0185), whereas the association with increased IGFBP4 was less strong (p = 0.0786)." (PMID 28443133, 2017). "IGFBP-1, IGFBP-3, IGFBP-4 are closely associated with diabetes and diabetic nephropathy." (PMID 35002740, 2021). "Future studies are needed to elucidate the link between ANGPTL8 and IGFBP4 and the mechanism of action through which they contribute to diabetes and its complications." (PMID 37762544, 2023). "Like other IGFBPs, IGFBP-4 plays an important role in diabetes mellitus and diabetic nephropathy." (PMID 35002740, 2021). "IGFBP-3, IGFBP-4, IGFBP-5, IGFBP-6 are involved in different kidney disease such as diabetes, FSGS and CKD physiological process as apoptosis proteins, IGFBP-7 has been used in clinical practice as a biomarker for early diagnosis and prognosis of AKI." (PMID 35002740, 2021). "Prevention of advanced glycation end products accumulation in the STZ-induced model of diabetes has been reported to inhibit overexpression of IGF1, IGFBP-1, and IGFBP-4 mRNAs, suggesting the role of glycation end products in activation of IGF1 renal expression in diabetes mellitus." (PMID 34943879, 2021).
prostate carcinoma (7 papers, 2008 to 2025). A carcinoma that arises from epithelial cells of the prostate gland. "Several studies have found that overexpression of IGFBP4 inhibited the cell growth in some cancers including prostatic cancer, colon cancer and breast cancer." (PMID 28946875, 2017). "Few evidences are reported about the role of IGFBP4 and 6 on prostate cancer proliferation." (PMID 36140255, 2022). "The upregulation of IGFBP4 (encodes for a protein that binds insulin-like growth factors I and II26), was shown to function as a potent tumor suppressor in hepatocellular carcinoma and delay tumor formation in prostate cancer cells." (PMID 33110154, 2020). "Interestingly, inhibition of IGFBP-4 expression in prostate cancer cells also lead to the suppression of cancer cell growth which may be caused by greatly increased levels of IGFBP-3 and -6 in these cells." (PMID 24175938, 2013). "IGFBP-4 is an important member of the IGFBP family of proteins and is expressed in some cancers, such as lung and prostate cancer cells." (PMID 28946875, 2017). "PAPP-A can hydrolyze IGFBP-4 to release free IGF-I and enhance its local biological effect; this regulatory mechanism also plays an important role in the progression of tumors such as prostate cancer." (PMID 41584612, 2025).
colon carcinoma (6 papers, 1997 to 2023). "To explore the role of the IGFBP-4 in prevention of colon cancer establishment, we simultaneously administered gene construct containing IGFBP-4 cDNA at the same time when the subcutaneous cancer was induced in nude mice." (PMID 17988381, 2007). "IGFBP-4 was shown to inhibit growth of some colon cancer cells." (PMID 36013453, 2022). "In this study we assessed the preventive role of IGFBP-4 in colon cancer in the form of gene therapy in vivo and found that IGFBP-4 did not prevent the establishment of cancer in HT-29 colon cancer model but it increased the cell death, apoptosis and decreased tumour proliferation." (PMID 17988381, 2007). "We assessed the effect of IGFBP-4 in prevention of development of colon cancer in vivo." (PMID 17988381, 2007). "Further experiments are needed to find out whether the IGFBP-4 gene therapy can be combined with chemotherapeutic agents in preventing the establishment of colon cancer in situations such as familial adenomatous polyposis." (PMID 17988381, 2007). "From our experiment, we conclude that IGFBP-4 gene therapy in the form localised gene transfer did not prevent colon cancer initiation and establishment but it increased in apoptosis and Bax protein expression and a decrease in tumour cellular mitosis." (PMID 17988381, 2007). "Nude mice were subcutaneously inoculated with HT-29 colon cancer cells and they were also simultaneously injected either gene construct containing mammalian expression vector pcDNA3 with or without IGFBP-4 gene or phosphate buffered saline." (PMID 17988381, 2007). "IGFBP-4 gene therapy could not prevent CRC in mice inoculated with HT-29 colon cancer cells, but an increased apoptosis was detected." (PMID 36013453, 2022). "This study showed that IGFBP-4 gene therapy did not prevent the establishment of colon cancer from HT-29 cells in nude mice but it resulted in an increase in apoptosis indicating IGFBP-4 may influence tumour growth or development but not cancer initiation." (PMID 17988381, 2007). "Colon cancer extracts were able to degrade exogenous IGFBP-2, IGFBP-3 and IGFBP-4, whereas normal tissue extracts were without effect on IGFBP-2." (PMID 9218734, 1997).
diabetic nephropathy (6 papers, 2016 to 2023). "Our results indicated that NGAL and IGFBP4 plasma levels are high in patients with diabetic nephropathy." (PMID 35148702, 2022). "This came in agreement with previous reports and it supports the potential involvement of IGFBP-4 in diabetic kidney disease." (PMID 35148702, 2022). "Collectively, our data showed people with DN to have elevated levels of IGFBP1 and IGFBP4, which comes in agreement with previous reports and suggests the elevation of these IGFBPs as indicative factors of a diabetic kidney disease." (PMID 31772941, 2019). "In this study, we examined levels of circulating ANGPTL4 in people with diabetic nephropathy (DN) and its association with established DN-associated proteins such as IGFBP1 and IGFBP4." (PMID 31772941, 2019). "Previous reports have demonstrated that serum Insulin-like growth factor binding protein 4 (IGFBP-4) was increased in diabetic nephropathy in both animal models and patients." (PMID 27019456, 2016). "Receiver Operating Characteristic (ROC) analysis was performed to determine the probable use of NGAL and IGFBP4 markers to differentiate between diabetic patients with or without diabetic nephropathy." (PMID 35148702, 2022).
glioma (6 papers, 2013 to 2023). A benign or malignant brain and spinal cord tumor that arises from glial cells (astrocytes, oligodendrocytes, ependymal cells). "On the contrary, the anti-tumorigenic and anti-angiogenetic functions of IGFBP-4 in glioma cells depend to its ability to induce dibutyryl cyclic AMP (dB-cAMP) that antagonize the VEGFs action in an IGF-independent manner." (PMID 33604294, 2020). "Furthermore, it was reported that the IGFBP4 expression has tumor promoting effects in renal cell carcinoma and glioma, suggesting a possible oncogenic role for IGFBP4." (PMID 35832140, 2022). "Likewise, Igfbp1 knock-down alleviates the hypoxia-induced growth retardation in zebrafish, whereas the IGFBP4 expression is induced by hypoxia in U87 glioma cells." (PMID 31354511, 2019). "Insulin-like growth factor-binding protein-4 (IGFBP-4) has been found to have anti-angiogenic functions in experiments and can attenuate the aggressiveness of gliomas, and is considered a potential candidate for glioma therapy." (PMID 37398678, 2023). "Using the polymerase chain reaction, GBM cell lines were found to express mRNA for IGFBP genes: IGFBP-1 in 42%, IGFBP-2 in 65%, IGFBP-3 in 97%, IGFBP-4 in 3%, IGFBP-5 in 74%, IGFBP-6 in 94%, and IGFBP-7 in 87% of glioma cell lines." (PMID 35832140, 2022). "The results from the Oncomine database showed that IGFBP2, IGFBP3, IGFBP4, and IGFBP5 were expressed at a higher level in tissues from patients with brain and CNS cancer than in normal tissues from healthy individuals." (PMID 35832140, 2022). "Based on the data from the Oncomine database, the transcriptional levels of IGFBP2, IGFBP3, IGFBP4, and IGFBP5 were observed to be elevated in brain and CNS cancer." (PMID 35832140, 2022). "IGFBP-3, IGFBP-4 and IGFBP-5 transcripts are significantly higher in GBM compared to low-grade gliomas or normal samples, supporting their role in the pathogenesis of gliomas." (PMID 33604294, 2020). "Overexpression of connexin-43 in C6 glioma cells results in decreased levels of IGFBP-3 and increased levels of IGFBP-4 and it may be responsible for the reduced proliferative capacity." (PMID 24175938, 2013).
hepatocellular carcinoma (6 papers, 2012 to 2024). A malignant tumor that arises from hepatocytes. "The IGF pathway has been implicated in carcinogenesis and the role of IGFBP-4 has been studied in a number of human malignancies, including lung, endocrine (thyroid and adrenal), breast, prostate, and hepatocellular cancers." (PMID 22264331, 2012). "In hepatocellular carcinoma, IGFBP4 as a novel tumor suppressor potently inhibits cell proliferation, invasion, and diminishes xenograft tumor growth in mice by the EZH2 and AKT pathways." (PMID 37433992, 2023). "In hepatocellular carcinoma (HCC), IGFBP4 was reported as a tumor suppressor that was negatively associated with cell invasiveness." (PMID 37349627, 2024).
melanoma (6 papers, 2008 to 2022). A malignant, usually aggressive tumor composed of atypical, neoplastic melanocytes. "Particularly in melanoma, one study compared primary and metastatic tumors and found increased protein levels of IGFBP4 in primary versus metastatic tumors." (PMID 35606887, 2022). "We found a concordant relationship between DNA methylation and transcriptional levels for genes from the malignancy (Pyroxd2 and Ptgfrn) and metastasis (Arnt2, Igfbp4 and Ptprf) signatures, which were both also correlated with melanoma prognosis." (PMID 35606887, 2022). "The diminished motility of MDA-MB-231 was similar to the abrogation of motility previously noted with the anti-PAPP-A and anti-IGFBP4 monoclonal antibodies in melanoma cells." (PMID 32792532, 2020). "Median IGFBP-3 expression in primary melanoma tumor specimens was 80%, while median IGFBP-4 expression in primary tumors was 70%." (PMID 19025658, 2008). "In the metastasis signature, Arnt2 and Igfbp4 genes, highly expressed and hypomethylated only in 4C11 + metastatic melanoma cells compared to melan-a, 4C and 4C11− cells, had their expression significantly increased in melan-a, 4C and 4C11− cells after 5azaCdR and 5azaCdR + TSA treatment." (PMID 35606887, 2022). "Furthermore, immunohistochemistry data from 132 melanoma patient tumor specimens (primary, n = 72; metastatic, n = 63) demonstrate that in the progression from primary to metastatic melanoma, IGFBP-4 expression decreases while integrin avb3 expression increases (data not shown)." (PMID 19025658, 2008). "In our study, we first found that up-regulation of IGFBP5 decreased HIF1α expression and the other IGFBPs family members, IGFBP2, IGFBP4, IGFBP6, and IGFBP7 to some extent in melanoma cells." (PMID 26010068, 2015). "Notably, IGFBP-4, the primary substrate of PAPPA was upregulated in mesenchymal-like melanoma cells." (PMID 25940796, 2015).
osteosarcoma (6 papers, 2013 to 2022). A usually aggressive malignant bone-forming mesenchymal neoplasm, predominantly affecting adolescents and young adults. "And osteosarcoma patients with high expression levels of IGFBP4 (HR = 0.56, P = 0.013) and TAGLN (HR = 0.52, P = 0.012) had better overall survival times than those with low expression levels." (PMID 35665757, 2022). "Osteosarcoma patients with high expression levels of IGFBP4 (HR = 0.56, P = 0.013) and TAGLN (HR = 0.52, P = 0.012) had better general survival times than those with low expression levels." (PMID 35665757, 2022). "In this study, the IGFBP4 gene was low expressed in osteosarcoma, and low expression had a poor prognosis." (PMID 35665757, 2022). "And LYN, TNC, TGFB2, IGFBP1were up-regulated in the osteosarcoma tissue samples, while IGFBP4, TAGLN, SERPINE1, ANPEP were down-regulated." (PMID 35665757, 2022). "Early studies demonstrated that IGF-1 stimulates osteosarcoma cell collagen I production and that this effect was attenuated through the action of the insulin-like growth factor-binding protein-4 (IGFBP4) in a concentration-dependent manner." (PMID 34069554, 2021). "Support Vector Machine (SVM) was performed to construct the correlation among the expression of IGFBP4, TAGLN, and osteosarcoma." (PMID 35665757, 2022). "It was found that the IGFBP4 gene and TAGLN gene were under-expressed in osteosarcoma, and when the two genes were under-expressed, patients had a poor prognosis." (PMID 35665757, 2022). "The relative expression levels of IGFBP4, SERPINE1, ANPEP and TAGLN were significantly lower in the osteosarcoma group compared with the normal group." (PMID 35665757, 2022). "By the Human Protein Atlas, protein expression of IGFBP4 and TAGLN in the osteosarcoma was lower than the normal (P < 0.05)." (PMID 35665757, 2022). "And the SVM presented that there exists strong relationship among the expression of IGFBP4, TAGLN, and osteosarcoma." (PMID 35665757, 2022). "In the current study, we evaluated the expression pattern of IGFBP4 and TAGLN in patient-derived osteosarcoma tissues." (PMID 35665757, 2022). "We also explored the clinical implications of IGFBP4 and TAGLN expression status in patients with osteosarcoma, and the animal experiment was performed to verify the role of IGFBP4 and TAGLN on the osteosarcoma." (PMID 35665757, 2022). "Based on the qPCR and immunofluorescence, IGFBP4 and TAGLN were down-regulated in the osteosarcoma tissue than the control group." (PMID 35665757, 2022). "Compared with the normal group, the relative expression of IGFBP4 and TAGLN in the osteosarcoma animal model was lower (P < 0.05)." (PMID 35665757, 2022). "We identified IGFBP4 and GAS6 as the most downregulated genes in osteosarcoma (average log fold changes of -4.43 and -4.29, respectively)." (PMID 23688189, 2013). "Both IGFBP4 and GAS6 expression have previously been shown to be downregulated in osteosarcoma cell lines (IGFBP4 in MG63, GAS6 in MG63 and SAOS2 cells)." (PMID 23688189, 2013). "IGFBP4 and TAGLN may be attractive molecular targets for osteosarcoma, opening a new avenue for research into the disease." (PMID 35665757, 2022). "This study showed that IGFBP4 and TAGLN were of low expression in patients with osteosarcoma." (PMID 35665757, 2022). "Through bioinformatics, IGFBP4 and TAGLN were identified as the hub genes of osteosarcoma." (PMID 35665757, 2022). "Furthermore, predictable value of IGFBP4 and TAGLN for the osteosarcoma was found via the support vector machine (SVM)." (PMID 35665757, 2022). "There existed strong value of IGFBP4 and TAGLN on the development and occurrence of osteosarcoma." (PMID 35665757, 2022). "Both IGFBP4 and GAS6 show high variability in expression in osteosarcoma cell lines and biopsies." (PMID 23688189, 2013).
osteosarcoma (continued). "Finally, IGFBP4 and TAGLN may be attractive molecular targets for osteosarcoma, opening a new avenue for research into the disease." (PMID 35665757, 2022). "However, effect of IGFBP4 and TAGLN on the survival of osteosarcoma is unclear." (PMID 35665757, 2022). "IGFBP4 and GAS6, which code for proteins that inhibit IGF1R signaling, showed the highest significant downregulation (log fold changes <−4) in a four-way analysis, in which osteosarcoma pretreatment biopsies or cell lines were compared with osteoblastic cultures (n=3) or MSCs (n=12)." (PMID 23688189, 2013). "However, the molecular mechanism of IGFBP4 and TAGLN on osteosarcoma has not been further explored in these studies." (PMID 35665757, 2022).